STARD10 (StAR related lipid transfer domain containing 10)
Description:
May play metabolic roles in sperm maturation or fertilization (By similarity). Phospholipid transfer protein that preferentially selects lipid species containing a palmitoyl or stearoyl chain on the sn-1 and an unsaturated fatty acyl chain (18:1 or 18:2) on the sn-2 position. Able to transfer phosphatidylcholine (PC) and phosphatidyetanolamline (PE) between membranes.
Synonyms: SDCCAG28; CGI-52; NY-CO-28; PCTP2
Tractability: PROTAC: its protein half-life has been measured.
Gene: Protein-coding gene on chromosome 11 (72,753,216 to 72,794,047, reverse strand). Ensembl gene ENSG00000214530.
Subcellular location: Cell projection, cilium, flagellum; Cytoplasm; Membrane
Subcellular location (Human Protein Atlas): Cytosol
Pathways (Reactome):
Metabolism: Synthesis of PC
Gene Ontology:
Molecular function: protein binding; lipid transporter activity; phosphatidylcholine binding; lipid binding
Biological process: phosphatidylcholine biosynthetic process
Cellular component: cytosol; intercellular canaliculus; membrane; microvillus; cytoplasm; motile cilium
Genetic constraint (gnomAD): Loss-of-function variants: 24 observed, 37.2 expected, observed/expected ratio (o/e) 0.65, 90% interval 0.47 to 0.91. The upper end of that interval is the gene's LOEUF score, 0.91, which puts it in group 3 of 6, group 1 being the genes least tolerant of losing a copy. Missense variants: 335 observed, 412.8 expected, observed/expected ratio (o/e) 0.81, 90% interval 0.74 to 0.89. Synonymous variants: 156 observed, 166.84 expected, observed/expected ratio (o/e) 0.94, 90% interval 0.82 to 1.07.
Homologues: Orthologues: chimpanzee STARD10 (99% identical), macaque STARD10 (99% identical), mouse Stard10 (97% identical), rat Stard10 (97% identical), guinea pig STARD10 (97% identical), dog STARD10 (97% identical), pig STARD10 (97% identical), rabbit STARD10 (96% identical), tropical clawed frog stard10 (69% identical), zebrafish stard10 (67% identical), Caenorhabditis elegans T28D6.7 (34% identical). Paralogues in human: PCTP (19% identical), STARD7 (17% identical).
Diseases named in the same sentence as STARD10 in open-access papers:
STARD10 is named in the same sentence as 14 diseases in open-access papers, as found by Europe PMC text mining. Sharing a sentence is not in itself a finding about the gene and the disease. The quoted sentences say what the papers report.
breast carcinoma (6 papers, 2009 to 2026). "Functionally, STARD10 overexpression enhanced HER2+ breast cancer cell proliferation, migration, invasion, and lipid droplets accumulation." (PMID 42296148, 2026). "This is the first report demonstrating that ethanol can modulate in dynamic manner the ERBB2 role through STARD10 involvement in breast cancer." (PMID 30611309, 2019). "Intriguingly, STARD10 was found to be co-expressed with ERBB2 in several breast carcinoma cell lines, suggesting a selective growth advantage and cellular transformation for tumor expressing both proteins." (PMID 30611309, 2019). "STARD10 is highly expressed at protein level in mouse mammary tumor, in 35% of primary breast carcinoma and in 64% of human breast cancer cell lines." (PMID 30611309, 2019). "In this paper we tried to elucidate the mechanism by which ERBB2/STARD10 crosstalk promotes ethanol induced cell growth and migration in breast cancer cells." (PMID 30611309, 2019). "The results suggest that the steadiness of STARD10 is important for regulating the proliferative activity in breast cancer and its dysregulation leads to an increase in cell proliferation and migration with consequent increase in neoplastic progression." (PMID 30611309, 2019). "Taken together, our data demonstrate that ethanol can modulate ERBB2’s function in breast cancer via a novel interplay with STARD10." (PMID 30611309, 2019). "Because STARD10 expression appears to be deregulated in several types of cancer including breast cancer, we examined STARD10 mRNA level in 38 independent breast cancer microarray datasets from the GEO database." (PMID 30611309, 2019). "We found that hsa-miR-21 and has-miR-96 forms the interaction model mostly with oncogenes, but hsa-miR-10b forms three interaction models with tumor suppressors, FOXO1, SERPINB5, and STARD10, to have statistical dependency on breast cancer." (PMID 28793339, 2017). "miR-661 is shown to regulate Nectin-1 and StarD10 in the disassembly of epithelial cell junctions in SNAI1-expressing breast cancer cells." (PMID 26512777, 2015). "STARD10 is a specific lipid carrier for PC and PE, is well-known to be overexpressed in Neu/ErbB2-induced mammary tumors in transgenic mice, in several human breast carcinoma cell lines, and in 35% of primary human breast cancers." (PMID 30611309, 2019). "Interestingly, STARD10 has been described to be highly expressed in 35–40% of ERBB2-positive breast cancers." (PMID 30611309, 2019). "The results suggest that a balanced level of STARD10 is important for regulating the proliferative activity in breast cancer and its dysregulation in either direction (increase or decrease) leads to an increase in cell proliferation and migration with consequent increase in neoplastic progression." (PMID 30611309, 2019). "MTT assay was performed to determine the effect of STARD10, ERBB2 and ethanol on cell proliferation, which revealed that STARD10 overexpression enhanced the viability of the mammary tumor cells compared to control in a manner similar to ethanol administration and ERBB2 overexpression." (PMID 30611309, 2019). "FOXO1, SERPINB5, and STARD10 are putative breast cancer suppressor." (PMID 28793339, 2017). "In another study, Vetter and coworkers showed that miR-661 expression in MCF7 breast cancer cells conditionally overexpressing the EMT master regulator SNAI1 contributes to breast cancer cell invasion by targeting cell-cell adhesion Nectin-1 and the lipid transferase StarD10 messengers." (PMID 22408395, 2012). "The aim of this study was to investigate the role of STARD10 and ERBB2 cross-talk in breast cancer as consequence of ethanol administration and elucidate the molecular mechanisms." (PMID 30611309, 2019).
breast carcinoma (continued). "Since our preliminary data proves that ethanol treatment causes STARD10 and ERBB2 upregulation in vivo and in vitro, we further explored the role of STARD10 in ethanol-induced tumor promotion to test the hypothesis that STARD10 and ERBB2 cooperate in ethanol induced breast cancer." (PMID 30611309, 2019). "hsa-miR-661 is known to be expressed at early time points of SNAI1-induced EMT and promote invasion of breast cancer cells by degrading two target genes, NECTIN1 (cell-cell adhesion protein), and STARD10 (lipid transferase)." (PMID 28793339, 2017). "FOXO1 is known to be regulated by miR-27a, miR-96, and miR-182 in breast cancer cells, SERPINB5 is regulated by miR-21, and STARD10 is regulated by miR-661." (PMID 28793339, 2017). "In normal breast tissues, STARD10 expression was not detectable at protein level, while in ERBB2 positive human breast cancer tissue, it was expressed in 30% of samples." (PMID 30611309, 2019).
type 2 diabetes (5 papers, 2017 to 2025). "The risk allele (C) of STARD10 rs11603334 for type 2 diabetes is positioned near the ARAP1 promoter." (PMID 41036138, 2025). "show the importance, for gene regulation, of a genomic region harboring GWAS variants that affect type 2 diabetes risk at the STARD10 locus." (PMID 33535042, 2021). "Risk alleles for type 2 diabetes at the STARD10 locus are associated with lowered STARD10 expression in the β-cell, impaired glucose-induced insulin secretion, and decreased circulating proinsulin:insulin ratios." (PMID 32416313, 2020). "Changes in STARD10 expression in carriers of type 2 diabetes risk alleles may consequently affect the β-cell lipid composition and alter granule maturation and, ultimately, insulin synthesis and secretion." (PMID 32416313, 2020). "Genetic variants near ARAP1 (CENTD2) and STARD10 influence type 2 diabetes (T2D) risk." (PMID 28132686, 2017). "Thus, β-cell STARD10 may be a useful therapeutic target in some forms of type 2 diabetes, particularly in risk allele carriers who may benefit from a tailored, pharmacogenetic approach." (PMID 32416313, 2020). "Using chromatin conformation capture, we show that an enhancer cluster in the STARD10 type 2 diabetes (T2D) locus forms a defined 3-dimensional (3D) chromatin domain." (PMID 33535042, 2021). "Module 84 contained three effector genes from the Type 2 Diabetes Knowledge Portal—ABCC8, SLC30A8, and G6PC2—and module 103 included two effector genes: PAX6 and STARD10." (PMID 37333221, 2023).
breast tumors (2 papers, 2019 to 2021). "Finally, we detected peptides from the 5′ UTR of STARD10, which also displayed higher abundance in a subset of breast tumors." (PMID 33888849, 2021).
diabetes (2 papers, 2018 to 2021). "In our recent studies, we used functional GWAS (fGWAS) to fine map a diabetes-associated credible set in the STARD10 (StAR-related lipid transfer protein 10) T2D GWAS locus, in which the risk haplotype has a global frequency of 86%." (PMID 33535042, 2021). "Similarly, the two strongest weighted loci in Cluster 2 are ARAP1, a locus at which diabetes risk is thought to be mediated by modulation of STARD10 expression in pancreatic beta cells, and SPRY2, a locus at which the closest gene, SPRY2, regulates insulin transcription." (PMID 30240442, 2018).
Glucose intolerance (1 paper, 2017). Glucose intolerance (GI) can be defined as dysglycemia that comprises both prediabetes and diabetes. "However, compared to wild-type controls, male StarD10+/– and StarD10–/– mice exhibited higher fed glycemia from 14 weeks and developed glucose intolerance from 16 weeks of age." (PMID 28132686, 2017).
Impaired glucose tolerance (1 paper, 2026). An abnormal resistance to glucose, i.e., a reduction in the ability to maintain glucose levels in the blood stream within normal limits following oral or intravenous administration of glucose. "Proteomic analysis revealed that individuals with impaired glucose tolerance (IGT) had reductions in proteins regulating glycolysis (PGK1, G3P), lipid metabolism (ACBP, ARF1), glucose transport (14-3-3B), and insulin secretion (STARD10, CAPDS) compared with normal glucose-tolerant (NGT) individuals." (PMID 41854718, 2026).
inflammatory bowel disease (1 paper, 2024). A spectrum of small and large bowel inflammatory diseases of unknown etiology. "Additionally, STARD10 is linked to resilience against Paratuberculosis, STX2 against Escherichia coli, CCR9 shows potential for treating inflammatory bowel disease, and BANK1 regulates innate immune signaling in B cells." (PMID 38684985, 2024).
Insulin resistance (1 paper, 2017). Increased resistance towards insulin, that is, diminished effectiveness of insulin in reducing blood glucose levels. "Given the existence of insulin resistance in global StarD10 mice, likely to be the result of changes in liver function, we reassessed the impact of variants near ARAP1 and STARD10 on this parameter in humans by consulting previously published data." (PMID 28132686, 2017).
mycobacterial infection (1 paper, 2025). "Additionally, the genes Mgll, Dgat2, Slc27a6, and Stard10 have been implicated in lipid metabolism, indicating that lipid metabolism may be disrupted in Gpr84−/− BMDMs during mycobacterial infection." (PMID 39858878, 2025).
pulmonary arterial hypertension (1 paper, 2021). Pulmonary arterial hypertension (PAH) is a group of diseases characterized by mean pulmonary artery pressure >20 mmHg and elevated pulmonary arterial resistance leading to right heart failure. "Several previous studies have shown that apoptosis play a vital role in pulmonary arterial hypertension, indicating that the association of miR-638 with PAH may be partially related to STARD10, a target gene of miR-638." (PMID 34987392, 2021).
tumor (4 papers, 2007 to 2026). "Subcutaneous implantation and tail vein injection were performed to evaluate the effects of STARD10 overexpression on tumor growth and lung metastasis in vivo." (PMID 42296148, 2026). "Moreover, STARD10 overexpression markedly accelerated tumor growth and lung metastasis in vivo." (PMID 42296148, 2026). "Alcohol administration increased STARD10, ERBB2 and p-ERK protein levels by 6.8-, 4.8- and 1.5-fold compared to control tumor tissues." (PMID 30611309, 2019). "Out of 11 ER target genes, four ER target genes showed significant differences between tumours with and without transcriptionally active NF-κB: GATA3 (P=0.001), MYB (P=0.004), HSD17β4 (P=0.030) and STARD10 (P=0.013)." (PMID 17700572, 2007).
cancer (3 papers, 2014 to 2025). A tumor composed of atypical neoplastic, often pleomorphic cells that invade other tissues. "These compounds’ binding energies and interaction profiles highlight their potential to modulate STARD10 activity, emphasising its critical role in cancer progression." (PMID 39790022, 2025). "The binding energies and interaction profiles suggest that these compounds can modulate the activity of STARD10, which plays a significant role in cancer progression." (PMID 39790022, 2025). "Some of the identified factors (such as TSPAN8, CXCL17, CRIP2, STARD10, CSNK2A1) and pathways (i.e. apoptosis, TGFβ, VEGF and ERK signaling) are known to participate in cancer as well as their identification here linked with airway remodeling in mustard lung." (PMID 24978043, 2014).
cardiovascular disease (1 paper, 2022). "The role of other genes such as NARS, PKDCC, ARHGDIG, STARD10, and MAPK12 expressed in the hypertrophy stage requires more investigation in cardiovascular disease." (PMID 35625658, 2022).
STARD10 also shares sentences with these, for which no sentence is quoted: Obesity (1 paper).